LINC00899 (long independently transcribed non-coding RNA 899)
Gene: Long non-coding RNA gene on chromosome 22 (46,039,907 to 46,048,412, reverse strand). Ensembl gene ENSG00000231711.
Diseases named in the same sentence as LINC00899 in open-access papers:
LINC00899 is named in the same sentence as 5 diseases in open-access papers, as found by Europe PMC text mining. Sharing a sentence is not in itself a finding about the gene and the disease. The quoted sentences say what the papers report.
breast carcinoma (2 papers, 2019 to 2020). "In the present study, we investigated role of LINC00899 in the progression of breast cancer and explored the underlying mechanisms." (PMID 31739288, 2019). "Additional studies are needed to assess the expression and function of LINC00899 in various subtypes of breast cancer to verify the role of LINC00899 in breast cancer." (PMID 31739288, 2019). "In the present study, we demonstrated that LINC00899 is downregulated in human breast cancer tissues and cell lines, and that overexpression of LINC00899 suppresses cell proliferation and invasion." (PMID 31739288, 2019). "Taken together, our data reveal that LINC00899 serves as a tumor suppressor restraining breast cancer cell growth and metastasis." (PMID 31739288, 2019). "Here, qRT-PCR analysis revealed that LINC00899 is significantly down-regulated in breast cancer tissues and cell lines, while in vitro assays showed that overexpression of LINC00899 significantly inhibits breast cancer cell growth and metastasis." (PMID 31739288, 2019). "To investigate the role of LINC00899 in breast cancer, we analyzed its expression in the cancer tissues and adjacent normal tissues using real-time qPCR." (PMID 31739288, 2019). "To shed light on the potential mechanism by which LINC00899 exerts its regulatory functions in breast cancer, we predicted miRNAs that might interact with LINC00899 using the predication software miRcode and RNA22." (PMID 31739288, 2019). "Further mechanistic studies revealed that LINC00899 may act as a tumor suppressor that exerts its antitumor effects by disrupting miR-425-mediated suppression of DICER1 during breast cancer development." (PMID 31739288, 2019). "Similarly, Transwell assays with Matrigel showed that LINC00899 overexpression suppressed breast cancer cell migration and invasion." (PMID 31739288, 2019). "Bioinformatics analysis was used to investigate the role of LINC00899 in breast cancer." (PMID 31739288, 2019). "This suggests LINC00899 levels have important prognostic value for breast cancer patients." (PMID 31739288, 2019). "Here, we found that LINC00899 is downregulated in breast cancer tissues and cell lines." (PMID 31739288, 2019). "Here, we hypothesize that LINC00899 may also serve as a ceRNA to implement its biological function in breast cancer." (PMID 31739288, 2019). "We found that LINC00899 is downregulated in human breast cancer tissues and cell lines, that its overexpression suppresses cell proliferation and invasion, and that its antitumor activity during breast cancer development reflects its ability to disrupt miR-425-mediated suppression of DICER1." (PMID 31739288, 2019). "Four of the breast cancer cell lines (not BT549 cells) exhibited apparently reduced levels of LINC00899, whereas MCF-10A cells showed high levels of LINC00899." (PMID 31739288, 2019).
acute myeloid leukemia (1 paper, 2020). Acute myeloid leukemia (AML) is a group of neoplasms arising from precursor cells committed to the myeloid cell-line differentiation. "LINC00899 is elevated in the serum and bone marrow of acute myeloid leukemia (AML) patients, therefore, serum LINC00899 may be a promising marker for the early diagnosis and prognosis of AML." (PMID 32117736, 2020).
multiple sclerosis (1 paper, 2020). A progressive autoimmune disorder affecting the central nervous system resulting in demyelination. "In GTEx brain samples, high TPPP expression is accompanied by low levels of linc00899, and in multiple sclerosis patients TPPP and linc00899 expression were negatively correlated." (PMID 32296040, 2020).
cancer (1 paper, 2019). A tumor composed of atypical neoplastic, often pleomorphic cells that invade other tissues. "Gene ontology (GO) terms and Kyoto Encyclopedia of Genes and Genomes (KEGG) pathway analysis indicated that LINC00899 is closely related to several cancer-associated processes, including tight junction- and metabolism-associated pathways." (PMID 31739288, 2019).
LINC00899 also shares sentences with these, for which no sentence is quoted: tumor (2 papers).